MTOR (mechanistic target of rapamycin kinase)
Diseases named in the same sentence as MTOR in open-access papers (continued):
Sharing a sentence is not in itself a finding about the gene and the disease.
endometrial cancer (continued). "As treatment for advanced and recurrent endometrial cancer shifts towards combined chemotherapy and immunotherapy, additional combination strategies, such as with mTOR inhibitors may be worth investigating." (PMID 37839313, 2023). "Based on what has been discovered regarding the molecular and genetic makeup of endometrial cancers, targeted therapies beyond mTOR and CDK4/6 have the possibility to increase activity when combined with hormonal therapy (e.g., MEK inhibitors and tyrosine kinase inhibitors)." (PMID 36980685, 2023). "Here, this study aimed to investigate whether AF promoted ferroptosis by regulating ROS/AMPK/mTOR to inhibit the viability and proliferation and promoted the apoptosis of endometrial cancer cells." (PMID 35635082, 2022). "Therefore, the key regulators in the PI3K/AKT/mTOR pathway are tightly regulated, and good targets in endometrial cancer for tumor therapy 15-17." (PMID 36483599, 2022). "Unique pathways of F-AD switch genes were associated with viral myocarditis, Hippo signaling pathway, endometrial cancer, insulin signaling, PI3K-AKT signaling, adherens junction, gap junction, cardiomyopathy, mTOR signaling, longevity, sphingolipid signaling, apoptosis, E. coli infection." (PMID 36389068, 2022). "Previous evidence showed that CCAT2 knockout repressed endometrial cancer cell growth and invasion by binding to miR‐216b, and miR‐216b could negatively regulate Bcl‐2 that could active the mTOR pathway." (PMID 35170195, 2022). "PI3K/Akt/mTOR pathway is crucial in various tumors, including endometrium carcinoma." (PMID 35205261, 2022). "Although CD47 has been involved in cancer progression, at the cell level in vitro CD47 was discovered to be a critical part in enhancing cell migration ability, viability, and inhibiting apoptosis in endometrial carcinoma cells via the PI3K_Akt_mTOR Signaling Pathway." (PMID 35281519, 2022). "PRMT6/miR-372-3p/Akt/mTOR signal pathway facilitated endometrial cancer process." (PMID 33869779, 2021). "Further studies are needed to better target PI3K/AKT/mTOR signaling in endometrial cancer." (PMID 33579221, 2021). "A specific endometrial cancer organoid line was most sensitive to everolimus (an inhibitor of mammalian target of rapamycin [mTOR]), which suggested a strong dependence on the PI3K-AKT pathway and was in line with mutations in the pathway’s signaling mediators (PTEN, PIK3CA, AKT1)." (PMID 32552764, 2020). "In addition, inhibition of mTOR has been shown to increase autophagy in endometrial cancer, consistent with our findings of reduced p-AKT levels." (PMID 33088426, 2020). "Therefore, metformin is thought as a mTOR inhibitor to reduce cellular proliferation in various type of cancer cell lines including endometrial cancer." (PMID 33172126, 2020). "Taking into consideration differences in mTOR pathway alterations between type I endometrial carcinoma and carcinosarcoma, supported by observed in present study resistance of carcinosarcoma cell lines to rapamycin, therefore comparing this studies seems to be doubtful." (PMID 33173419, 2020). "Besides, CD47 down-regulation reduced PI3K, Akt, and mTOR expression in endometrial carcinoma cells further confirmed this." (PMID 32984001, 2020).
endometrial cancer (continued). "Moreover, treatment of cells with RAD001, a novel mTOR inhibitor, resulted in low mTOR phosphorylation and suppressed the cell proliferation of progestin-resistant endometrial cancer cells by activating autophagy." (PMID 31850214, 2019). "On the other hand, Zhuo and colleagues demonstrated that miR-205 was upregulated in a progesterone-resistant (PR) sub-cell line and induced apoptosis through repressing autophagy process by targeting tumor suppressor PTEN through AKT/mTOR signaling in endometrial cancer." (PMID 31850214, 2019). "Furthermore, the activation of mTOR signaling pathway has been proven to be beneficial to patients suffering from endometrial cancer." (PMID 31262977, 2019). "Our earlier work has established that overactive mTOR drives the growth of endometrial cancer." (PMID 27980219, 2017). "We will be focusing on the uses of anti-angiogenic agents, epidermal growth factor receptor (EGFR) inhibitors, HER2/neu antibodies, and phosphoinositide 3-kinase (PI3K)-PTEN-AKT-mammalian target of rapamycin (mTOR) pathway inhibitors in endometrial cancer (seeTable 1)." (PMID 28184290, 2017). "Similarly, a concentration of at least 1 mM metformin was required to suppress the growth of two types of endometrial cancer-derived cell lines, one of which has a mutation in PTEN in the PI3K/AKT/mTOR signaling pathway." (PMID 28525374, 2017). "This study was focused on the fact that the mTOR pathway could be involved in the resistance to hormonal therapy in endometrial cancers." (PMID 28008141, 2017). "To further investigate the stimulation effect of PFOA on EMT in vivo, we assessed whether PFOA-mediated activation of mTOR signaling contributed to tumorigenesis in a xenograft mouse model of endometrial cancer." (PMID 27589685, 2016). "The PI3K/AKT/mTOR pathway is frequently altered in endometrial cancer." (PMID 27589685, 2016). "HIF1A, NF-kB and PI3K/mTOR might be potential treatment targets in aggressive endometrial cancers with presence of tumor necrosis." (PMID 26485755, 2015). "Recent studies and our own data indicate that UPR and mTOR signaling may be significant in long-term tamoxifen exposure-induced endometrial cancer." (PMID 25788989, 2015). "Previous studies have demonstrated up-regulation of the PI3K/AKT/mTOR pathway as a mechanism of resistance to hormone therapy, and clinical trials combining hormone therapy with mTOR inhibitors have shown promise in breast and endometrial cancers." (PMID 26021831, 2015). "The mean expression of mTOR in tamoxifen-associated endometrial cancer patients was significantly higher compared with the non-tamoxifen group." (PMID 25788989, 2015). "Type I endometrial cancer harbors altered PI3K/AKT/mTOR signaling pathway constituents." (PMID 25760378, 2015). "Consequently, the PI3K-Akt-mTOR signaling pathway is activated in many patients with endometrial cancer." (PMID 25734181, 2015). "As indicated by our data, HIF1A, NF-kB and PI3K/mTOR might be potential targets in aggressive endometrial cancers with presence of tumor necrosis." (PMID 26485755, 2015). "Currently other mTOR inhibitors are being tested in the therapy of advanced endometrial cancer." (PMID 24745019, 2014). "Therefore, EGF and HER2 signaling inhibitors, angiogenesis inhibitors and molecular-targeted drugs including mTOR inhibitors are used for endometrial cancer." (PMID 23291663, 2013). "Our data suggest that a dual inhibitor of PI3K/mTOR might be a more promising therapeutic strategy than a single mTOR inhibitor in endometrial cancer." (PMID 22662154, 2012). "Our data demonstrate that in these cells, temsirolimus treatment promotes a further increase in Akt phosphorylation, indicating that signaling through the pro-survival PI3K/Akt pathway is likely how these endometrial cancer cell lines eventually circumvent mTOR inhibition." (PMID 22039466, 2011).
endometrial cancer (continued). "Chemotherapy-naïve endometrial cancer patients treated with temsirolimus, an mTOR inhibitor, achieved a preliminary response rate of 26% according to the National Cancer Institute of Canada; this result was not correlated to PTEN status as evaluated by immunohistochemistry." (PMID 20148071, 2010). "Some genes related with endometrial carcinoma prognosis have become a hopeful target for therapies in endometrial carcinoma, these targeting genes include mTOR inhibitors, EGFR tyrosine kinase inhibitors (erlotinib), and monoclonal antibodies to Her-2/neu (trastuzumab)." (PMID 20613958, 2010). "However, a more recent study found that treatment with Asparanin A, isolated from stems and spears of ASP, leads to induction of cell cycle G0/G1 arrest, activation of caspases pathway and reduction of mitochondrial membrane potential through the PI3K/AKT/mTOR pathway in endometrial cancer cells." (PMID 34336674, 2021). "Also, CLDN6 regulates the PI3K/AKT/mTOR signaling pathway in HEC-1B endometrial carcinoma cells and EGFR/AKT/mTOR signaling pathway in HepG2 cells, but the mechanisms of how CLDN6 affects the signaling pathway in both HEC-1B and HepG2 cells remain to be verified." (PMID 34948213, 2021). "In summary, taxol treatment can inhibit the Ishikawa cells and Ishikawa-TAX cells through PI3K/Akt/mTOR signaling pathway, and therefore regulating PI3K/Akt/mTOR pathway may been a promising therapeutic direction for the clinical treatment of drug-resistant endometrial carcinoma." (PMID 30175145, 2018). "In addition to identifying well-known drivers, CHASM identified potential drivers not previously associated with endometrial cancer, in biologically relevant pathways: viz MTOR in the PI3K pathway and GSK-3B in the Wnt signalling pathway)." (PMID 23325621, 2013). "Additionally targeted therapies such as mTOR inhibitors show promise in endometrial cancer." (PMID 23864861, 2013). "Both the mTOR inhibitor RAD001 and the AKT inhibitor terameprocol (M4N) downregulated IGFBP2 expression in endometrial cancer cells by targeting the Sp1 transcription factor, resulting in synergistic inhibition of tumor growth." (PMID 40746599, 2025). "Here, we sought to explore the mechanism and efficacy of a multi-node PI3K/mTOR/AKT pathway inhibition approach in breast and endometrial cancer models." (PMID 40360883, 2025). "Baicalein, a natural flavonoid, shows potent anti-tumor activity against endometrial cancer by inhibiting cell proliferation and suppressing the AMPK/PI3K/mTOR pathway." (PMID 41303544, 2025). "In KLE endometrial cancer (EC) cells, the flavonoid amentoflavone was evaluated for its ability to induce ferroptosis via the ROS/AMPK/mTOR pathway." (PMID 41140697, 2025). "Endometrial cancer (EC) is the most common gynecological malignancy, frequently characterized by PTEN deletion, activation of the AKT/mTOR pathway, and limited effective treatment options for recurrent and advanced patients." (PMID 39990670, 2025). "Insulin-like growth factor binding protein 2(IGFBP2) is overexpressed in endometrial cancer tissue and acted through the PI3K/AKT/mTOR pathway." (PMID 40746599, 2025). "Metformin, a well-known mTOR inhibitor through AMPK activation, has been previously studied for its potential in treating endometrial cancer." (PMID 41303544, 2025). "IHC expression of Akt, mTOR, and Pax-2 was positively correlated with ICC expression within the endometrial carcinoma cohort, benign lesion cohort, and normal cohort." (PMID 40357279, 2025).
endometrial cancer (continued). "This study demonstrated that adding vistusertib (mTOR inhibitor) to anastrozole improved the progression-free rate at 8 weeks (8wk-PFR), overall response rate, and PFS for patients with endometrial cancer and had manageable adverse events." (PMID 38791945, 2024). "Testing the clinical benefit of ONC201 in women with recurrent or metastatic endometrial cancers, especially those with alterations in the PI3K/mTOR pathway." (PMID 37589388, 2024). "In endometrial cancer, Brass has been reported to activate the ROS/AMPK/mTOR pathway to inhibit the viability and invasion of cancer cells and promote their ferroptosis." (PMID 38583115, 2024). "In type I endometrial carcinomas, the PI3K/Akt/mTOR pathway exhibits a hyperactivation, leading to inhibition of autophagy induction that appears to be related to cell proliferation and survival." (PMID 39596186, 2024). "The most well-studied downstream pathway in endometrial cancer is the phosphatidylinositol-3-kinase (PI3K)/Akt and mammalian target of rapamycin (mTOR)." (PMID 36980685, 2023). "A study also showed that HSPB7 was downregulated in endometrial carcinoma (EC) and influenced EC cell proliferation and metastasis via the PI3K/AKT/mTOR signaling pathway (Xing, Wu & Wang, 2023)." (PMID 38084139, 2023). "The top three canonical pathways identified by IPA to be the most different in endometrial cancers across racial groups (EIF2 signaling, regulation of eIF4 and p70S6K signaling and mTOR signaling) are all involved in the regulation of protein synthesis." (PMID 35887124, 2022). "Toward endometrial cancer, the effect of the prodrug of EGCG (ProEGCG) exhibited anti-proliferative, pro-apoptotic, and anti-tumor actions via ERK/JNK, Akt and PI3K/AKT/mTOR/HIF1α signaling pathway." (PMID 35860020, 2022). "Artesunate induced apoptosis and cell cycle arrest of endometrial cancer cells by down-regulating ER-α expression and activating liver kinase B1 (LKB1)/AMPK/mammalian target of rapamycin (mTOR) pathways." (PMID 35635082, 2022). "In several cancers, including endometrial cancer, changes in cholesterol-rich lipid rafts induce the activation of the PI3K/AKT/mTOR pathway in the malignant process, which is central to modulating cell migration, metabolism, proliferation, and survival." (PMID 36483599, 2022). "ProEGCG, a derivative of EGCG, significantly reduced the phosphorylation of ERK and Akt in endometrial cancer cells, suggesting that the PI3K/Akt/mTOR and MAPK signaling pathways play an important function in the apoptotic pathway." (PMID 35243817, 2022). "The inflammatory pathways predominantly reported in the literature on progression of endometrial cancer are the MAPK, JAK/STAT3 and PI3K/AKT /mTOR pathways." (PMID 34951691, 2022). "PI3K/Akt/mTOR signaling pathway activation via upregulation of CD47 expression enhances cellular viability and migration ability but suppresses endometrial carcinoma cell apoptosis." (PMID 35281519, 2022). "In conclusion, the dual PI3K/mTOR inhibitor PQR309 inhibits cell viability in two-dimensional (2D) and three-dimensional (3D) cell culture models in endometrial cancer cells." (PMID 34831139, 2021). "It was previously shown that ADSL levels modulate Akt phosphorylation in endometrial cancer and that TCA cycle defects, specifically the accumulation of α-ketoglutarate (αKG), as well as ROS increase can activate the mTOR signaling pathway 7,50-53." (PMID 33754045, 2021). "The enriched pathways play a pivotal role in the occurrence and development of endometrial cancer, thus representing attractive and promising therapeutic targets, such as PARP inhibitors, and mTOR inhibitors." (PMID 34837690, 2021).
endometrial cancer (continued). "We present a case of acquired mTOR resistance, following targeted AKT inhibition, and subsequent response to mTOR1/2 inhibitor in a patient with metastatic endometrial cancer, the first documented response to ATP-competitive mTOR inhibition in this setting." (PMID 34853384, 2021). "In endometrial carcinoma, there is an effect on the activation of the PI3K/AKT/mTOR transduction cascade via overexpression of ERα." (PMID 33996538, 2021). "We identified AKT/mTOR inhibition and ERK phosphorylation and nuclear pERK accumulation as key factors that can modulate endometrial cancer cell line sensitivity to sulforaphane." (PMID 32443471, 2020). "We, therefore, chose to evaluate the roles of AKT, mTOR, and ERK signaling in the mechanism of sulforaphane in endometrial cancer cell lines." (PMID 32443471, 2020). "Proteomic analysis identified alterations in AKT, mTOR, and ERK kinases in the networks of sulforaphane effects in the Ishikawa endometrial cancer cell line." (PMID 32443471, 2020). "In type I endometrial cancer, as autophagy is repressed by activated PI3K/AKT/mTOR signaling pathway, the proliferation of tumor cells becomes facilitated, indicating that autophagy inhibits the development of tumors." (PMID 32684843, 2020). "CCL18 seems to activate mTOR via the PI3K→Akt/PKB pathway, as shown by experiments on endometrial cancer cells." (PMID 33114763, 2020). "We found that CD47 up-regulation increased PI3K, Akt and mTOR expression in endometrial carcinoma cells, suggesting that CD47 exerted oncogenic effects in endometrial carcinoma via up-regulating the PI3K/Akt/mTOR signaling pathway." (PMID 32984001, 2020). "Itraconazole is a common antifungal agent that inhibited Hedgehog and AKT/mTOR signaling transducers as well as WNT/β-catenin signaling and showed a dose- and time-dependent suppression of cell proliferation in human endometrial cancer cell lines." (PMID 31850214, 2019). "Treatment with rapamycin, an mTOR inhibitor, antagonized the effects of PFOA and reversed the effects of PFOA activation in a xenograft mouse model of endometrial cancer." (PMID 27589685, 2016). "In our previous study in simvastatin on endometrial cancer, we found that treatment with simvastatin resulted in inhibition of the MAPK pathway and exhibited differential effects on the AKT/mTOR pathway in the ECC-1 and Ishikawa cells." (PMID 26503475, 2016). "It is likely that women with endometrial cancer may also benefit from metformin's antiproliferative effects, especially in obese patients who may have elevated circulating insulin and glucose levels as well as activation of the mTOR pathway in their endometrial tumors." (PMID 25417601, 2015). "In endometrial cancer cells, the RAS-RAF and PI3K-Akt-mTOR pathways are activated via receptor tyrosine kinases, including involvement of PTEN in the PI3K-Akt-mTOR pathway." (PMID 23291663, 2013). "Metformin inhibits the mTOR pathway with activation of AMPK, and consequently this drug has potential for prevention and treatment of endometrial cancer." (PMID 23291663, 2013). "Fourth-generation progestins, metformin, mTOR inhibitors, microRNAs and HDAC inhibitors are promising candidates for treatment of endometrial cancer." (PMID 23291663, 2013). "We examined the antitumor effect of NVP-BEZ235—a dual PI3K/mTOR inhibitor—and RAD001—an mTOR inhibitor—in 13 endometrial cancer cell lines, all of which possess one or more alterations in PTEN, PIK3CA, and K-Ras." (PMID 22662154, 2012). "In this study, we firstly evaluated the antitumor effect of a dual PI3K/mTOR inhibitor, NVP-BEZ235, and an mTOR inhibitor, RAD001 (everolimus), in a panel of endometrial cancer cell lines." (PMID 22662154, 2012). "In the context of endometrial cancer, metformin has been shown to suppress cell proliferation, at least in part, by modulating key signaling pathways such as AMP-activated protein kinase (AMPK) and the PI3K/mTOR axis." (PMID 41303544, 2025).